KRAS (KRas proto-oncogene, GTPase)
Diseases named in the same sentence as KRAS in open-access papers (continued):
Sharing a sentence is not in itself a finding about the gene and the disease.
lung adenocarcinoma (continued). "STK11/LKB1 mutation has been identified as a main driver of anti-PD1 resistance in KRAS-mutant lung adenocarcinoma, and loss of LKB1 has been linked to decreased numbers and function of T cells in the TME." (PMID 33013881, 2020). "Analysis of lung adenocarcinoma demonstrated that the most prevalent G12C mutation of KRAS was associated with smoking, and was a major driver, while the G12D and G12V mutations are far less effective and classified as mini drivers." (PMID 32725342, 2020). "KRAS mutation is the most common gain-of-function alteration, accounting for ~30% of lung adenocarcinomas in Western countries and about 10% of Asian lung adenocarcinomas." (PMID 33178836, 2020). "Most driver alterations in lung adenocarcinomas, such as mutations in KRAS and EGFR, ALK fusions, and loss of NF1 function, confer activation of the Ras/Raf/ERK pathway." (PMID 32158759, 2020). "For example, inconsistent mutation status of KRAS have been discovered between the primary and metastatic sites of lung adenocarcinoma, while the status of EGFR mutation is relatively consistent on the contrary." (PMID 33537237, 2020). "Kirsten Ras Sarcoma Viral Oncogene Homolog (KRAS) harbors activating mutations in about a third of lung adenocarcinomas." (PMID 33114576, 2020). "KRAS mutations are present in approximately 30% of Caucasian individuals and 10% of East Asian individuals with lung adenocarcinoma." (PMID 32633046, 2020). "We found a good correlation between methylated HOXA9 and mutated KRAS in plasma from patients with lung adenocarcinoma." (PMID 33322500, 2020). "We herein present the first report of a patient with two simultaneously resected metachronous lung adenocarcinomas in the right upper lobe, each with a distinct driver mutation in the KRAS gene identified by targeted next generation sequencing (NGS)." (PMID 32415761, 2020). "KRAS, the oncogene causing 10 ~ 30% of lung adenocarcinomas, was highly expressed in the neuroendocrine cells." (PMID 32727470, 2020). "Most patients with NSCLC were enrolled in the extension phase of the trial (n = 13, 41.9%), all of them with lung adenocarcinoma harboring mutation of KRAS as defined per study protocol." (PMID 32436621, 2020). "KRAS mutations were detected by NGS in tumor tissue from 34/48 (70.8%) of patients with lung adenocarcinoma." (PMID 33322500, 2020). "KRAS mutations account for approximately 30% of lung adenocarcinomas in Western countries and for 10–15% of cases in Asia." (PMID 32560574, 2020). "KRAS mutations are the most frequent gain-of-function alterations in patients with lung adenocarcinoma (LADC) in the Western world." (PMID 32548736, 2020). "For example, preclinical findings have identified that inhibition of the interleukin-6 (IL-6)/STAT3 pathway can also inhibit tumor growth with EGFR mutation in NSCLC and suppress KRAS-driven lung adenocarcinoma." (PMID 33537237, 2020). "The lung adenocarcinomas exhibiting integrin upregulation were highly enriched in mutation and mRNA upregulation of KRAS or EGFR, and were linked to poor clinical prognosis compared to those carrying alterations in single oncogene." (PMID 32793596, 2020). "Serine/threonine kinase 11 (STK11, or liver kinase B1, LKB1) is a tumor suppressor that is often found mutated in lung adenocarcinoma, especially in presence of co-occurring KRAS mutations." (PMID 33114576, 2020). "For example, in KRAS-mutant lung adenocarcinoma, STK11/LKB1 mutation is associated with resistance to ICB treatment." (PMID 32110280, 2020).
lung adenocarcinoma (continued). "KRAS mutations are the most common oncogenic driver mutations and occur in ~30% of lung adenocarcinoma (LAD)." (PMID 32108165, 2020). "Two studies enrolled surgically resected lung adenocarcinoma patients and found that those with KRAS mutation tumors had worse disease free survival and OS compared with wildtype patients." (PMID 32607238, 2020). "Ruxolitinib treatment was associated with an increase in CD8+ T cells in pancreatic cancer xenograft models and a decrease in myeloid-derived suppressor cells in KRAS-mutated lung adenocarcinoma models, indicating an impact on immune activity." (PMID 33521321, 2020). "The KRASG12C mutation is highly prevalent in patients suffering from lung adenocarcinoma (13% of total lung adenocarcinoma) and account for >50% of all KRAS mutant cases." (PMID 32560574, 2020). "In in vivo xenograft models of neuroblastoma, HCC (in which there was a JAK1 S703I mutation), and KRAS-mutated lung adenocarcinoma, among others, ruxolitinib treatment significantly inhibited tumor growth." (PMID 33521321, 2020). "The first molecules to target this site were inhibitors of KRAS G12C mutant that is most prevalent in non-small cell lung cancer and lung adenocarcinomas, in which presence of KRAS mutations mean worse prognosis, and elevated resistance for certain therapies." (PMID 32715349, 2020). "The KRAS encoded transforming protein has been associated with various malignancies, including lung adenocarcinoma, pancreatic ductal carcinoma, and CRC." (PMID 32235004, 2020). "Given the close association between αv integrins and KRAS-mediated growth of lung adenocarcinomas, we examined the clinical outcomes of patients from this group." (PMID 32793596, 2020). "Patients with surgically resected lung adenocarcinoma (n = 72) were enrolled, including 12 patients with KRAS mutations and 60 patients with EGFR mutations." (PMID 31783917, 2019). "Concluding, this is the largest study assessing EGFR and KRAS mutation status in the Brazilian lung adenocarcinoma population." (PMID 30824880, 2019). "To do this, we focused on NSCLC cells that are enriched for KRAS mutations occurring in ∼33% of lung adenocarcinoma." (PMID 30927008, 2019). "Herein, we reported the association of EGFR and KRAS mutational status with clinicopathological features from approximately 500 Brazilian lung adenocarcinoma patients attended at the Barretos Cancer Hospital." (PMID 30824880, 2019). "Oncogenic KRAS mutations are major drivers of lung adenocarcinoma (LAC), yet the direct therapeutic targeting of KRAS has been problematic." (PMID 30833304, 2019). "The mutational frequency of EGFR and KRAS genes in lung adenocarcinoma varies worldwide per ethnicity and smoking." (PMID 30824880, 2019). "Our data adds confirmation with earlier work that lung squamous cell carcinoma shows a rare presence of two ubiquitous mutations seen in lung adenocarcinomas, KRAS and EGFR, are rare in lung squamous cell carcinoma." (PMID 31749831, 2019). "KRAS mutation is known to exist in one-third of lung adenocarcinomas (LUADs), but quite rare in MSGTs." (PMID 30634950, 2019).
lung adenocarcinoma (continued). "While a great deal of attention has been focused on the role of mutated KRAS as a common driver mutation for lung adenocarcinoma, little is known about the role of KRAS in regulating normal human airway differentiation." (PMID 31399087, 2019). "Gain-of-function mutations in KRAS are present in ∼25% of human lung adenocarcinomas and are truncal events, acquired early in disease development." (PMID 30760495, 2019). "Lung adenocarcinoma with mutations in the oncogene KRAS remains to be the most aggressive molecular subtype of lung malignancy with generally poor prognosis and resistance to most therapies." (PMID 31001473, 2019). "Carcinogenic Kirsten rat sarcoma viral oncogene homolog (KRAS) mutation is the most common gain-of-function alteration, accounting for ~30% of lung adenocarcinomas in western countries and about 10% of Asian lung adenocarcinomas." (PMID 31612108, 2019). "KRAS mutations play a major role in the pathogenesis of lung adenocarcinoma, representing > 25% of the driver mutations for lung adenocarcinomas." (PMID 31399087, 2019). "Its loss cooperates with KRAS mutations in lung adenocarcinoma progression by opposing to the oxidative stress barriers during tumorigenesis." (PMID 31544066, 2019). "In conclusion, we assessed the clinicopathological and ethnic impact of EGFR and KRAS mutations in the largest series reported of Brazilian lung adenocarcinomas." (PMID 30824880, 2019). "Hotspot KRAS mutations, at codons 12/13, are described in approximately 20% lung adenocarcinomas and are known to be associated with tobacco consumption." (PMID 30824880, 2019). "The purpose of this study is to compare the characteristics measured with dual-energy spectral computed tomography (DESCT) in lung adenocarcinoma patients who have KRAS and EGFR gene mutations." (PMID 31783917, 2019). "This is because KRAS mutations are detected in 25% of lung adenocarcinomas, which are associated with reduced survival in NSCLC patients, as well as resistance to EGFR TKIs." (PMID 31428570, 2019). "DESCT would be a potential tool to differentiate lung adenocarcinoma patients with a KRAS mutation from those with an EGFR mutation." (PMID 31783917, 2019). "Similar to Western population, the two most ubiquitous mutations were those in EGFR and KRAS in the case of lung adenocarcinoma samples." (PMID 31749831, 2019). "Several driver mutations have been described, in the recent years, in lung adenocarcinomas including those affecting KRAS (15-25%) and EGFR (10-35%)." (PMID 29464099, 2018). "Using a CRISPR/Cas-9-based approach in a mouse model of KRAS-driven lung adenocarcinoma, it was examined the effect of KEAP1 loss in lung adenocarcinoma development and hyperactivates NFE2L2 expression." (PMID 30060526, 2018). "The most incident molecular alterations in lung adenocarcinoma, namely, KRAS mutations, EGFR mutations and ALK translocations, have been linked to MAPK activation." (PMID 29731995, 2018). "KRAS mutations are associated with advanced tumor progression and clinical aggressiveness, forming a persistent risk of lung adenocarcinoma and implying to be an early event in the tumorigenesis process." (PMID 29868480, 2018). "This is in contrast with the previous study that showed a higher frequency of KRAS mutations in lung adenocarcinomas associated with UIP." (PMID 30445777, 2018).
lung adenocarcinoma (continued). "Two sets of triplex knockdown vectors were constructed; one for G12D, G12V and G12R (51%, 30% and 12% of PDAC KRAS mutations, respectively) and another one for G12C, G12D and G12V (prevalent in colorectal and lung adenocarcinoma)." (PMID 29851957, 2018). "The mutual exclusivity of BRAF and KRAS mutations in AAHs and the disparate pattern of mutations in the paired lung adenocarcinomas suggest divergent pathways in the pathogenesis of preneoplastic lesions of lung adenocarcinomas." (PMID 30060526, 2018). "Of the associations involving signatures linked to extrinsic mutational processes, signature 4, linked to smoking, was associated with KRAS G12C (CCA > CAA) in lung adenocarcinoma and with CTNNB1 D32Y (TCC > TAC) in liver cancer." (PMID 29748584, 2018). "In lung adenocarcinomas, the KRAS mutation is a major oncogenic mutation frequently associated with the EZH2 mutation." (PMID 34991274, 2018). "For example, in lung adenocarcinoma, ~30% of tumors carry a mutation in the KRAS gene and ~15% carry a mutation in EGFR, but these mutations are mutually exclusive." (PMID 29854275, 2018). "Conditional EZH2 knock-out (KO) mice were also used to demonstrate that EZH2 inactivation increased lung adenocarcinoma aggressiveness in mice carrying the KRAS mutation." (PMID 34991274, 2018). "The levels of OX40 and OX40L were not consistently associated with major clinicopathogical variables, level of T-cell infiltration or with the presence of oncogenic mutations in EGFR/KRAS in lung adenocarcinomas (cohort#3)." (PMID 30400835, 2018). "Analysis of these types of mutations, particularly in EGFR and KRAS, is typically part of the work-up of lung adenocarcinoma patients." (PMID 30115026, 2018). "Loss of the pulmonary lineage specifier NKX2-1 augments the growth of KRAS-driven lung adenocarcinoma and causes pulmonary to gastric transdifferentiation." (PMID 30475207, 2018). "Recently, Liu and colleagues confirmed an increased mRNA expression, telomerase activity and telomere length in lung adenocarcinoma cells with KRAS mutations." (PMID 29464099, 2018). "KRAS mutations in lung adenocarcinoma were also reported to be associated with co-mutations in STK11/LKB1 (the KL subgroup)." (PMID 29486723, 2018). "In the last years, the deregulation of ErbB2/ErbB3 machinery is also emerging as an oncogenic trait of lung adenocarcinoma with mucinous pattern, a tumor subtype that is otherwise associated with KRAS mutations." (PMID 29515761, 2018). "S100A11 protein was selectively expressed in NSCLC and displayed a particularly prominent effect in KRAS-mutated lung adenocarcinomas." (PMID 29607329, 2018). "We found that PD-L1 expression was associated with KRAS mutation both in the human lung adenocarcinoma cell lines and tissues." (PMID 28451792, 2017). "Current guidelines lack comprehensive information on the metastatic site-specific role of KRAS mutation in lung adenocarcinoma (LADC)." (PMID 28051122, 2017). "In conclusion, our study found PD-L1 expression is correlated with KRAS mutation in lung adenocarcinoma." (PMID 28451792, 2017). "Although the mechanism(s) and/or tumor biological significances were unclear, high mesothelin expression was associated with KRAS gene mutation in lung adenocarcinoma." (PMID 28460459, 2017). "For example, KRAS mutations are frequently detected in lung adenocarcinomas in smokers, whereas genetic alterations in EGFR, ALK, ROS1, and RET are frequently detected in lung adenocarcinomas in non-smokers." (PMID 28894699, 2017).
lung adenocarcinoma (continued). "A similarly strong trend toward poor prognosis was also reported in lung adenocarcinoma with KRAS G12 V mutations." (PMID 29273082, 2017). "In order to investigate the association between PD-L1 expression and KRAS mutation status, we conducted experiments in human lung adenocarcinoma cell lines and tissue." (PMID 28451792, 2017). "KRAS mutations are detected in approximately 20–25% of lung adenocarcinoma and 4% of squamous cell lung carcinoma." (PMID 28451792, 2017). "We have recently reported on the usefulness of cfDNA to monitor responses to treatment of KRAS-mutated lung adenocarcinoma." (PMID 28445137, 2017). "The oncogene KRAS is mutated in 20-30% of lung adenocarcinomas, particularly in heavy smokers and in the Caucasian population." (PMID 28938691, 2017). "Although KRAS mutations are common in both colorectal and lung adenocarcinomas, the finding of the same mutation in both tumours strongly supported that the pulmonary tumour was a metastasis." (PMID 28347348, 2017). "KRAS mutations occur most frequently in lung adenocarcinomas and less frequently in the squamous cell carcinoma subtype." (PMID 29285236, 2017). "We observed 28.4% EGFR mutations and 13% KRAS mutations in lung adenocarcinoma patients, consistent with our previous report." (PMID 27998968, 2017). "KRAS is the most frequently activated oncogene in lung adenocarcinoma, and was mutated in 32% of cases." (PMID 28380052, 2017). "The prevalence of KRAS mutation in lung adenocarcinoma in Asian and Western patients is approximately 11 and 26%, respectively." (PMID 28451792, 2017). "In the present study, we demonstrated that PD-L1 expression was positively correlated with KRAS mutation both in the cell lines and tissue of lung adenocarcinoma." (PMID 28451792, 2017). "We treated A549 lung adenocarcinoma cells containing mutations in KRAS (homozygous G12S mutation) with either ERK1/2 or MEK inhibitors (SCH772984 and PD0325901, respectively) prior to stimulation with EGF, similar to the protocols that we used for HeLa cells." (PMID 28982763, 2017). "They identified 17 microRNAs that were differentially expressed between EGFR-mutated and EGFR-wild-type lung adenocarcinomas, and 3 microRNAs differentially expressed between KRAS-mutated and KRAS-wild-type lung adenocarcinomas." (PMID 28486396, 2017). "In public dataset GSE31210, low FSTL1 RNA level was associated with lung adenocarcinoma patients with ALK-fusion or KRAS mutation compared to those with EGFR mutation or EGFR/KRAS/ALK triple-negative tumors." (PMID 28852126, 2017). "In Asian patients, the rate of EGFR mutations was higher, while KRAS mutations rate was lower in lung adenocarcinoma compared with that in Westerns." (PMID 29290981, 2017). "The results showed that MAP4K4 was drastically elevated in lung adenocarcinoma independently of KRAS or EGFR mutation status." (PMID 28306189, 2017). "In case of lung adenocarcinoma high-level of mesothelin expression is associated with aggressiveness, poor prognosis and KRAS gene mutation status." (PMID 28460459, 2017). "Patient #1 was a 59-year-old male with an extensive smoking history who harboured a KRAS G12D mutated stage IV lung adenocarcinoma with diffuse metastases." (PMID 26883990, 2016). "The tumor cell lines with wild type EGFR evaluated here, H441 and A549, harbor a mutated version of the KRAS proto-oncogene, a genetic feature with 30% prevalence among lung adenocarcinomas." (PMID 27248176, 2016).